IL17A (interleukin 17A)
Diseases named in the same sentence as IL17A in open-access papers (continued):
Sharing a sentence is not in itself a finding about the gene and the disease.
diabetes (continued). "Various pathological features mediated by diabetes were significantly reduced in Il-17a −/− mice." (PMID 35392087, 2022). "Diabetes-induced retinal vascular leakage may be mediated by IL-17A regulation of neutrophil elastase and its activity because Il-17a gene deletion greatly attenuated the increase in neutrophil elastase levels of diabetic-retina." (PMID 35392087, 2022). "We previously reported that diabetes-mediated IL-17A enhanced ROS production in the retina, which was significantly decreased when the constitutively expressed IL-17 receptor was blocked in photoreceptor cells or when IL-17A was systemically ablated." (PMID 34456740, 2021). "Previous studies in the NOD model show that IL-17A and IL-17F expression correlates with increased autoimmune-mediated type I diabetes and pharmacological inhibition of Th17 cells prevented the development of diabetes in these mice." (PMID 34478449, 2021). "The diabetes-induced caspase-3 activity in the retinas was attenuated by IL-17A gene ablation." (PMID 34750361, 2021). "If anti-IL-17A was administered systemically, it could potentially halt the systemic progression of diabetes and some of its complications." (PMID 33919327, 2021). "Nonhealing wounds associated with diabetes are characterized by a prolonged inflammatory stage, and we found that IL-17A expression was significantly elevated in the ob/ob PU model but suppressed due to upregulation of KLF4." (PMID 34568499, 2021). "In this study, diabetes was induced in WT and IL-17A KO mice by STZ administration." (PMID 33691614, 2021). "Since there is an FDA approved anti-IL-17A drug available, it is possible that this drug could be used to halt the progression of diabetes and its complications." (PMID 33919327, 2021). "We discovered that diabetes stimulates neutrophils and Th17 cells to produce IL-17A." (PMID 32429598, 2020). "The increase in Th17 cytokines (such as IL-17A) may promote the secretion of proinflammatory factors and infiltration of macrophages and aggravate the diabetes-induced renal damage in DN." (PMID 33344651, 2020). "Similarly, diabetes-mediated IL-17A enhances VEGF production, which probably leads to neovascularization seen in proliferative diabetic retinopathy." (PMID 32429598, 2020). "However, clinical diabetes studies have provided evidence that IL-17A is continuously produced in the blood of both Type I and Type II diabetics." (PMID 32429598, 2020). "Two months after diabetes was confirmed, sera were collected for IL-17A ELISA analysis." (PMID 32429598, 2020). "There are no studies in the literature investigating the expression of proinflammatory(IFN-γ, TNF-α, IL-17A) and anti-inflammatory (IL-4, IL-10) cytokines in serum ofpatients with type 2 diabetes mellitus submitted to duodenojejunal bypass surgery withileal interposition without gastric resection." (PMID 26734798, 2015). "IL-17A deficient NOD mice do not develop diabetes, while blocking IL-17 with monoclonal antibodies protected young NOD mice from diabetes development." (PMID 24013901, 2013). "Therefore, γδ T cell–mediated promotion of Treg accumulation and functional restoration via IL-17A secretion may represent a potential strategy for future diabetes immunotherapy." (PMID 41341586, 2025). "In addition, diabetes increases the expression of IL-17A in the retina and serum." (PMID 37274105, 2023). "Similarly, diabetes-mediated IL-17A enhanced VEGF production so that preventing IL-17A production may be a potential treatment to delay the progression of DR." (PMID 35392087, 2022). "The development of diabetes caused transcriptional activation of the mammalian target of rapamycin protein kinase gene, as well as increased mRNA expression of the pro-inflammatory cytokines IL1β and IL17A, but did not affect Foxp3 mRNA expression." (PMID 32341701, 2020).
diabetes (continued). "In parallel, an anti-inflammatory effect of inulin administration on DPN in diverse stages of diabetes was unveiled in this study by reducing pro-inflammatory LPS, IL-6, TNF-α and IL-17A and elevating anti-inflammatory IL-10." (PMID 41264657, 2025). "The expressions of IL17A, ACE, TLR4, and IL6 are up-regulated with diabetes that promote the progression of gangrene, whereas the expressions of FGF2 and IGF1 are down-regulated." (PMID 40657379, 2025). "The expressions of IL17A, MMP2, IL10 and IL6 are up-regulated with diabetes that promote the progression of OP, whereas the expressions of FGF2 and VEGFA are down-regulated." (PMID 38250601, 2024). "In terms of SCFAs, for flaxseed oil exerted anti-diabetes action on streptozotocin-nicotinamide-induced rats, the acetic acid was negatively correlated with TNF-α, IL-1β, IL-6, and IL-17A." (PMID 39403395, 2024). "Conversely, when IL-17A was systemically neutralized in the db/db diabetic mice (black), VEGF was significantly decreased 2- and 6-months after diabetes was confirmed." (PMID 36675261, 2023). "Yet, when IL-17A was systemically ablated in the IL17A-/- STZ-diabetic mice (black), VEGF was significantly decreased to ~45 pg/mL 2- and 8-months post-diabetes." (PMID 36675261, 2023). "IL-17A was neutralized in the retina of STZ-diabetic C57BL/6 mice with one 50 μg/mL intravitreal injection of anti-IL-17A; 1 week after diabetes was confirmed." (PMID 36675261, 2023). "Other studies support the beneficial effects of IL-17A reduction in experimental DN in other mice models, as STZ-induced diabetes and autoimmune diabetes in NOD mice." (PMID 35370692, 2022). "Alteration in the level of pro-inflammatory cytokine (especially the IL-17A, IL-23 and IFN-γ) in T1D patients imply its significance as a potential pathogenesis marker, thereby extending the threat of developing diabetes related complications later in life." (PMID 27575603, 2016). "Additionally, the synergistic effect of IL-17A with IL-21 and IFN-γ has been reported to promote diabetes development." (PMID 40979706, 2025). "Additionally, CXCL1, CCL22 and IL-17A significantly differed between APMB and ARMB when correlated with diabetes, dialysis, metastatic infection, or cardiac vegetation." (PMID 39966757, 2025). "Treatment with antibodies against IL-17A has been shown to inhibit disease in NOD mice, and Th17 cells have been shown to drive pancreatic inflammation and their transfer into NOD.scid mice induced diabetes, but only after converting to Th1 cells." (PMID 40607421, 2025). "Recent studies have found that diabetes-mediated IL-17A enhances VEGF production in the retina, Muller glial cells, and retinal endothelial cells, and that IL-17A induces retinal endothelial cell proliferation and can enhance VEGF-dependent vascular neovascularization." (PMID 38711982, 2024). "Irrespective of the presence of diabetes, the cerebral expression of IL-17A and PD-1 revealed a strong correlation with cerebral parasite load." (PMID 37719029, 2023). "Third, DAPA modulated systemic inflammation via regulation of the inflammatory mediators, including G-CSF, GM-CSF, IL-1β, and IL-17A in the LPS-treated rats with and without diabetes." (PMID 37376131, 2023). "Further, A1C levels were significantly higher in both untreated and anti-IL17A-treated diabetic mice than their non-diabetic controls 6 weeks after diabetes was confirmed (and 1 week after the anti-IL-17A intravitreal injection)." (PMID 36674854, 2023). "Blood glucose and kidney function were not significantly different in WT and IL-17A KO mice without diabetes." (PMID 33691614, 2021). "IL-17A serum levels were increased significantly in experimental DN model of T1DM, and kidney injury is more severe in IL-17A knockout mice with STZ-induced diabetes." (PMID 34221188, 2021). "Similarly a significant increase has been identified in IFN-γ and IL-17A level in the lungs of patients infected with MERS-CoV and diabetes." (PMID 33746897, 2021).
diabetes (continued). "However, because diabetes induces systemic IL-17A production that has been determined to play a pivotal role in the progression of multiple diabetic complications, it would be beneficial to identify a therapeutic that could halt systemic IL-17-dependent pathology and cross the blood–retina-barrier." (PMID 32429598, 2020). "Anti-IL-6 (0.01 mg/kg b.wt., for 5 days) or anti-IL-17A (0.1 mg/kg b.wt., for 5 days) were administered to IDDM rats within 1 day after diabetes manifestation (blood glucose > 7.5 mmol/l), either alone or in combination with anti-TCR (0.5 mg/kg b.wt., for 5 days) in a double or triple fashion." (PMID 32106855, 2020). "The potential explanation of this discrepancy is an additive effect of IL17F to diabetes pathogenesis, since the blocking antibodies were not specific to IL17A." (PMID 24013901, 2013). "Hence, 50 μg/mL of non-toxic, anti-IL-17A was administered weekly to mice that were hyperglycemic and later analyzed 2- and 6-months post-diabetes." (PMID 36674854, 2023). "Weekly intraperitoneal injections of 100 μL of saline containing 10 μg/mL, 25 μg/mL, or 50 μg/mL of anti-IL17A was administered to non-diabetic (wild-type heterozygous Leprdb mice) and Leprdb Type II diabetic mice; 1 week after diabetes was confirmed with an FBG score greater than 275 mg/dL." (PMID 36674854, 2023). "Wherein diabetes-mediated IL-17A production was inhibited by: an anti-IL-17A intravitreal injection in STZ-Type I diabetic mice, weekly intraperitoneal injections of anti-IL-17A in db/db-Type II diabetic mice, or systemically ablated in IL17A-/- STZ-diabetic mice." (PMID 36675261, 2023). "However, our current findings suggest that Th17 cells are the primary source of diabetes-mediated IL-17A, which enhance retinal pathology and the onset of non-proliferative diabetic retinopathy." (PMID 33919327, 2021). "However, in diabetes, IL-17A is constantly produced and inflammation does not halt, which can lead to kidney failure, heart disease, or vision loss." (PMID 33919327, 2021). "In the present study, we observed that the synbiotic combination decreased the key cytokine IL-6 among other proinflammatory markers (IL-8, IL17a and IFNγ) after only 30 days of treatment in healthy middle-aged volunteers without any suspicion of type 2 diabetes mellitus and cardiovascular diseases." (PMID 33514774, 2021). "Therefore, the purpose of the study was to determine the mRNA expression levels of mTOR, Foxp3, IL1β, and IL17A genes in rat parapancreatic adipose tissue with experimental streptozotocin-induced diabetes mellitus, with or without metformin administration." (PMID 32341701, 2020). "Moreover, treatment with neutralizing anti-IL-17A in NOD mice prevented diabetes when treatment started at 10 weeks of age, but not at earlier stages." (PMID 31963845, 2020). "Seventeen patients with type 2 diabetes mellitus under clinical management weresubmitted to surgery and blood samples were collected before and six months aftersurgery for evaluation of the serum profile of proinflammatory (IFN-γ, TNF-α,IL-17A) and anti-inflammatory cytokines (IL-4, IL-10)." (PMID 26734798, 2015). "Consequently, a refined selection comprising seven genes (MMP2, MMP9, IL17A, IL10, FGF2, IL6 and VEGFA) and eleven pharmacological agents has emerged, exhibiting promise in delivering therapeutic effects aimed at mitigating the occurrence of OP in individuals afflicted with diabetes." (PMID 38250601, 2024). "No other significant associations were found between diabetes’ duration and evaluated cytokine parameters including IFN-γ+ PBMCs and IFN-γ MFI on CD3+ PBMCs; IL-6+ and CD3+IL-6+ PBMCs and IL-6 MFI on CD11b+ PBMCs; myeloid IL-17A+ PBMCs; CD11b+ and myeloid PBMCs." (PMID 36766809, 2023).
diabetes (continued). "The non-response cohort was older, more likely to have diabetes, and had higher levels of D-D polymers, Pro-BNP, direct bilirubin, and inflammatory markers, including ferritin, C-reactive, procalcitonin, IL-6, IL-10, and IL-17A than the response cohort." (PMID 41426569, 2025).
colorectal cancer (250 papers, 2010 to 2026). A primary or metastatic malignant neoplasm that affects the colon or rectum. "The expression of interleukins IL-8, IL-17A, and IL-33 in colorectal cancer demonstrates a strong association with the depth of tumor invasion across histological layers." (PMID 40725273, 2025). "IL-17A is also associated with more aggressive forms of colorectal cancer due to its pro-inflammatory activity and its involvement in tumor progression, particularly in the context of K-RAS mutations." (PMID 40725273, 2025). "The expression and interaction of interleukins IL-8, IL-17A, and IL-33 in colorectal cancer are closely associated with the degree of tumor invasion and play a pivotal role in disease progression." (PMID 40725273, 2025). "The expression of interleukins IL-8, IL-17A, and IL-33 in colorectal cancer is significantly associated with the degree of tumor differentiation, and their interplay appears to influence tumor progression." (PMID 40725273, 2025). "Another clinical analysis suggested that the activation of IL-17A signaling is associated with the failure of anti-PD-1 therapy in patients with colorectal cancer." (PMID 38022654, 2023). "For instance, both IL-17A and IL-22 have been associated with human colorectal cancer, and the increase in IL-17-producing cells has been proven to be an independent prognostic marker in human colorectal cancer." (PMID 35203436, 2022). "Higher interleukin-17A mRNA levels were associated with better overall survival rates and the early tumor stage, indicating a protective role of interleukin-17A in colorectal cancer." (PMID 36098359, 2022). "Although IL-17A and IL-17F were clarified as risk factors for colorectal cancer during the most recent decades, the concrete reasons were unclear." (PMID 35410225, 2022). "Other studies showed that high expression of RORγt, which is essential for IL-22 production, and IL-17A, which is commonly found in association with IL-22, indicates poor prognosis in patients with colorectal cancer." (PMID 28492497, 2017). "Some studies have previously shown that IL-17A and IL-17F polymorphisms, respectively rs2275913 and rs763780, are associated with gastric or colorectal cancer risk." (PMID 28347290, 2017). "Our data further reveal a correlation of Il17a and Rorc with Foxp3 expression in ovarian cancer-associated and colorectal cancer-infiltrating cells (the expression of Il17a in primary colorectal cancer cells is undetectable), respecitvely." (PMID 28290453, 2017). "The presence of IL-17A in colorectal cancer, hepatocellular carcinoma and NSCLC is generally associated with poor prognosis, whilst the presence of IL-17A in ovarian carcinoma and esophageal squamous cells carcinoma is associated with anti-tumor response." (PMID 28715437, 2017). "Several studies suggest that interleukin-17 (IL-17A or IL-17 or cytotoxic T-lymphocyte-associated protein 8) plays a major role in colorectal cancer progression and in the resistance to anti-VEGF treatment in murine models or chemotherapy." (PMID 28347290, 2017). "In fact, we showed that IL17A G197A polymorphism was positively correlated with an increased risk of developing colorectal cancer." (PMID 26083022, 2015). "This study demonstrated that the expression patterns of interleukins IL-8, IL-17A, and IL-33 are significantly associated with the histological grade and depth of tumor invasion in colorectal cancer, offering valuable insights into tumor aggressiveness and immune dynamics." (PMID 40725273, 2025). "Again, the increased IL-17A levels in the blood are linked with the aggressiveness of pancreatic adenocarcinoma, non-small cell lung cancer, thyroid tumors, laryngeal squamous cell carcinoma, and colorectal carcinoma." (PMID 38816694, 2024).
colorectal cancer (continued). "The effect of immune checkpoint inhibitors on IL-17A is not limited to γδ T cells, as human CD4+ T cells increase IL-17A after anti–PD-1 exposure and IL-17A–producing cells in general are associated with anti–PD-1 resistance in melanoma, lung, and colorectal cancer." (PMID 36480166, 2023). "Hence, this meta-analysis was conducted to first explore the association between IL-17A rs2275913 and IL-17F rs763680 polymorphisms and colorectal cancer." (PMID 35410225, 2022). "In conclusion, this meta-analysis displayed a significant association between the IL-17A rs2275913 polymorphism and susceptibility to colorectal cancer among Asians and Caucasians, which provided a potential risk factor for colorectal cancer for the two populations." (PMID 35410225, 2022). "As another important cytokine produced by ILC3s, IL-17A has been implicated in human colorectal cancer, and increased IL-17-producing cells could independently predict worse clinical outcomes." (PMID 31781671, 2019). "Notably, IL-17A polymorphisms were associated with increased risk of colorectal cancer development when comparing patients to healthy controls in Iranian and Tunisian populations." (PMID 28347290, 2017). "In addition, it has been shown that elevated serum levels of IL-17A may be associated with the development and metastasis of many tumors, especially colorectal cancer." (PMID 41142781, 2025). "The IL-17A rs2275913 polymorphism may be an independent risk factor contributing to colorectal cancer susceptibility, while the IL-17F rs763780 polymorphism may decrease susceptibility to colorectal cancer." (PMID 35410225, 2022). "Indeed, the mutated allele A of IL17A G197A polymorphism increases the risk of colorectal cancer." (PMID 26083022, 2015). "Chronic inflammation-driven colorectal cancer (CRC) is critically mediated by interleukin-17A (IL-17A)-dependent immune responses and nuclear factor-κB (NF-κB) signaling, which promote immune cell infiltration and tumor progression." (PMID 41751882, 2026). "Collectively, these results emphasize the relevance of IL-8, IL-17A, and IL-33 in the mechanisms of tumor invasion and support their potential utility as biomarkers and therapeutic targets in colorectal cancer management." (PMID 40725273, 2025). "A newly proposed framework—the complement/neutrophil/IL-1β–myeloid cell/IL-17A axis—further clarifies the involvement of the complement system in colorectal cancer progression." (PMID 41267807, 2025). "Interleukin 17 receptor A (FC = 0, p = 2.50E-02) is the receptor for interleukin-17A, which is a pro-inflammatory cytokine related to the rapid malignant progression and treatment resistance of colorectal cancer." (PMID 40709343, 2025). "Collectively, these results support the potential utility of IL-8, IL-17A, and IL-33 as biomarkers for assessing tumor behavior and as possible targets for personalized therapeutic interventions in colorectal cancer." (PMID 40725273, 2025). "The expression patterns of interleukins IL-8, IL-17A, and IL-33 in colorectal cancer vary according to tumor grade, playing a significant role in disease progression and prognosis." (PMID 40725273, 2025). "In colorectal cancer (CRC) models, IL-17A-deficient mice are protected from tumor invasion, and elevated levels of IL-17A are observed in the peripheral blood and tumor tissues of CRC patients." (PMID 40370457, 2025). "IL-17A accelerates colorectal cancer progression via regulating matrix metalloproteinases (MMPs) expression." (PMID 38430256, 2024). "As a stimulator of VEGFA production in tumors, IL-17A has been identified as angiogenesis-promoting in several types of cancer, including non-small-cell lung cancer and colorectal cancer." (PMID 38515019, 2024). "Previous studies have confirmed that IL-17A can accelerate the development of lung cancer, colorectal cancer, and even cervical cancer." (PMID 38430256, 2024).